TGFBR2 (transforming growth factor beta receptor 2)
Diseases named in the same sentence as TGFBR2 in open-access papers (continued):
Sharing a sentence is not in itself a finding about the gene and the disease.
squamous cell carcinoma (9 papers, 2005 to 2024). A carcinoma arising from squamous epithelial cells. "Associations between somatic TGFBR2 alterations and cancer progression occur in a range of solid tumor types, including gastric, bladder, and squamous cell carcinoma." (PMID 29383146, 2017). "Knocking down Elmo1 impairs metastasis of carcinoma cells to the lung, thereby providing insights into the mechanisms of progression of Tgfbr2-deficient invasive transition zone squamous cell carcinoma." (PMID 28219480, 2017). "However, some studies have proved that the mice with mutations in TGFBR2 have enhanced potential in tumor metastasis, and TGFBR2 receptor inhibitors enable reduced lung metastasis in squamous cell carcinoma." (PMID 39364312, 2024). "In general, downregulation of ZEB1, RECK, TGFBR2 and BMPR2, as well as upregulation of CDK4, CCNE2, EZH2 and DNMT1 has been shown in lung adenocarcinoma and/or squamous cell carcinoma." (PMID 27588394, 2016). "Mice lacking Tgfbr2 in stratified epithelia expressing Keratin 14 (K14) develop spontaneous squamous cell carcinoma (SCC) at the transition zone between the anal canal and rectum." (PMID 28219480, 2017).
liver cancer (8 papers, 2018 to 2024). An epithelial or non-epithelial malignant neoplasm that arises from the liver. "Deletion or downregulation of Tgfbr2 is related to the progression of various types of tumors, including liver cancer." (PMID 38212325, 2024). "The ChIP-seq of GABPA-expressing leukemic K562 and liver cancer HepG2 cells identified a total of 6,810 gene promoters bound by GABPA, and five genes were overlapped based on the integrated analyses above, among which was TGFBR2." (PMID 35549739, 2022).
lung adenocarcinoma (8 papers, 2005 to 2024). A carcinoma that arises from the lung and is characterized by the presence of malignant glandular epithelial cells. "As a result, a causal relationship between TGFBR2 (cause) and lung adenocarcinoma (consequence) was found." (PMID 39364312, 2024). "Previously, we showed the loss of Tgfbr2 in the non-invasive murine inducible lung adenocarcinoma model (Kras+/−Tgfbr2−/−) induces a highly invasive phenotype associated with lymph node metastasis and poor survival." (PMID 35332150, 2022). "To explore mechanisms involved in lung adenocarcinoma, we investigated the influence of the TGF-β1 and TGFBR2 polymorphisms on the risk of lung adenocarcinoma in a population-based case–control study." (PMID 25928368, 2015). "Although this study highlights the potential of TGFBR2 as a protective biomarker in lung adenocarcinoma (LUAD), it does have certain limitations." (PMID 39364312, 2024). "TGFBR2 can inhibit proliferation and migration of lung adenocarcinoma cell line A549 and promote apoptosis of A549 cells." (PMID 39364312, 2024). "To investigate the pre-clinical utility of aurora kinase inhibitors and to evaluate its efficacy in suppressing invasive lung adenocarcinoma, we treated the transgenic invasive LUAD mouse model of KrasG12D mutation and inducible Tgfbr2 deletion with AMG900." (PMID 35332150, 2022). "Subsequently, we used lung adenocarcinoma as the exposure factor and TGFBR2 as the outcome." (PMID 39364312, 2024). "TGFBR2 is included in the human lung adenocarcinoma indolence signature (FDR = 0.0016)." (PMID 35332150, 2022). "We examined the overlay of human lung adenocarcinoma gene signatures with murine gene expression from invasive (Tgfbr2−/−) and non-invasive (Tgfbr2wt) tumors and show that the pro-invasive and indolence signatures classify tumors from 11 mice into two groups that exactly match their Tgfbr2 status." (PMID 35332150, 2022). "The aim of this study was to test whether TGF-β1 C509T and TGF-β receptor II (TGFBR2) G-875A polymorphisms were associated with lung adenocarcinoma in nonsmoking females." (PMID 25928368, 2015). "Screening of instrumental variables using 5×10−8, r2 = 0.001; kb=10,000 conditions yielded five instrumental variables associated with lung adenocarcinoma but not with TGFBR2, IVW analysis revealed no significant causal effect of LUAD on TGFBR2 expression levels (p > 0.05)." (PMID 39364312, 2024).
Stroke (8 papers, 2009 to 2025). Sudden impairment of blood flow to a part of the brain due to occlusion or rupture of an artery to the brain. "Evans blue leakage increased at different time points after stroke in mice with EC-specific loss of the Tgfbr2 gene, even up to RP118D after stroke." (PMID 40667795, 2025). "Immunofluorescence statistics revealed an increase of NeuN+ neurons after stroke in EC-specific overexpression of the Tgfbr2 gene group, indicating that more neurons survived." (PMID 40667795, 2025). "Tgfb1 and Tgfbr2 mRNAs showed extremely high levels (10- to 57-fold over controls) at day 14 in post-stroke rats." (PMID 24672479, 2014). "This network of interactions included three genes, BMP6, TGFBR2, TGFBR3 with a functional role in the TGF-beta pathway and one gene (SELP) associated with stroke in the general population." (PMID 20401335, 2009). "Thus, EC-specific overexpression of the Tgfbr2 gene promotes CBF restoration after stroke, through the generation of E-pericytes." (PMID 40667795, 2025). "However, one third of the genes were increased with suboptimal timing in aged rats, either on day 3 post-stroke (Adam17, Gpc3, Mmp14, Nid2, Tagln, Wnt5b) or on day 14 after stroke (Col4a2, Col8a1, Cthrc1, Cxcl1, Gpc3, Tgfbr2)." (PMID 23251410, 2012). "Increasing the number of E-pericytes by EC-specific overexpression of the Tgfbr2 gene reduces BBB leakage, increases CBF, promotes angiogenesis, protects neurons, and enhances brain self-recovery after stroke." (PMID 40667795, 2025). "E-pericytes deletion by specific endothelial cells (ECs) knockout of the Tgfbr2 gene aggravates blood-brain barrier (BBB) leakage and neurological deficit after stroke." (PMID 40667795, 2025). "Endothelial cell (EC)-specific overexpression of the Tgfbr2 gene reinforces blood-brain barrier (BBB) function and neurological recovery after stroke." (PMID 40667795, 2025). "Stroke is also directly associated with variants in TGFBR3 and indirectly associated with variants in transforming growth factor, beta receptor II (TGFBR2), which have essential, non-redundant roles in TGF-betạ signaling." (PMID 20401335, 2009).
autoimmune disease (7 papers, 2012 to 2023). A disorder resulting from loss of function or tissue destruction of an organ or multiple organs, arising from humoral or cellular immune responses of the individual to their own tissue constituents. "Furthermore, depletion of TGFBR2 specifically in CD4+ T cells leads to early onset lethal autoimmune disease, further substantiating the anti-inflammatory role of TGFβ." (PMID 27270652, 2017). "Among them, TGFBR1, TGFBR2, CCL5, CD48, CD244A, and CD72 have been reported to be closely related to the pathophysiologic processes of autoimmune diseases." (PMID 35515003, 2022).
lymphoma (7 papers, 2009 to 2026). A malignant (clonal) proliferation of B- lymphocytes or T- lymphocytes which involves the lymph nodes, bone marrow and/or extranodal sites. "Consistent with the predicted ligand–receptor signalling, TGFBR2 knockdown in CD4+ T cells increased HBx‐overexpressing lymphoma cell apoptosis, while reducing CD4+ T cell apoptosis and enhancing proliferation and effector cytokine secretion." (PMID 41492119, 2026). "Using the RNA-seq data of 100 leukemia/lymphoma cell lines, we screened the expression levels of TGFb-pathway members and detected strong activities of the TGFb-receptor gene TGFBR2 in BCP-ALL cell lines, which may reflect the physiological significance of this pathway therein." (PMID 39202339, 2024). "Moreover, while regulation of TGFBR2 by promoter CGI methylation has previously been reported in lymphoma, a role for promoter hypomethylation in dysregulation of that pathway was previously unknown." (PMID 19505326, 2009).
non-small cell lung carcinoma (7 papers, 2015 to 2024). A group of at least three distinct histological types of lung cancer, including non-small cell squamous cell carcinoma, adenocarcinoma, and large cell carcinoma. "YAP and EZH2 act cooperatively to impair the tumor suppressor activity of TGFBR2 in non-small cell lung cancer, and the interaction between YAP and EZH2 participates in the transcriptional repression of key cell cycle regulators." (PMID 38245781, 2024). "MiR-9-5p elicited potential as a catalyst for invasiveness and metastasis by targeting TGFBR2 in non-small cell lung cancer." (PMID 33451320, 2021). "Consistent with this idea, previous studies have indicated that increased TGFBR2 expression is associated with resistance to ALK and EGFR inhibitors in non-small cell lung carcinoma." (PMID 33837205, 2021). "For instance, miR-9-5p suppresses TGFBR2 expression to accelerate the progression of non-small cell lung cancer." (PMID 31827394, 2019). "Additionally, miR-9-5p has been identified to facilitate the proliferation, migration, and invasion of non-small cell lung cancer cells by targeting and negatively regulating the TGFBR2 expression." (PMID 33451320, 2021). "Fang and colleagues have reported that miR-30c-2-3p targeted TGFBR2 and USP15 in non-small cell lung cancer (NSCLC) cells, leading to the inactivation of TGF-β signaling." (PMID 36606578, 2023).
osteoarthritis (7 papers, 2018 to 2025). A noninflammatory degenerative joint disease occurring chiefly in older persons, characterized by degeneration of the articular cartilage, hypertrophy of bone at the margins and changes in the synovial membrane. "LncRNA FGD5-AS1 controlled miR-302d-3p and TGFBR2 expression and caused inhibition of osteoarthritis development." (PMID 37779916, 2023). "LncRNA PART1 sponged miR-590–3p and regulated TGFBR2/Smad3, resulting in regulation of viability and apoptosis of chondrocytes in osteoarthritis." (PMID 37779916, 2023). "In addition, the knockout of Tgfbr2 in nestin-positive skeletal progenitors reduced the development of osteoarthritis in an anterior cruciate ligament transection (ACLT) osteoarthritis mouse model." (PMID 40141345, 2025).
colorectal tumors (6 papers, 2013 to 2024). "About 90% of MSI colorectal tumors exhibit inactivating frameshift mutations in a polyadenine (A10) tract in exon 3 of Transforming Growth Factor Beta Receptor Type 2 (TGFBR2) gene." (PMID 31454892, 2019). "Missense mutations affecting TGFBR2 were also identified in 15% of microsatellite stable colorectal tumors and in several other tumor types, including breast, prostate and renal cell carcinoma." (PMID 31454892, 2019). "Biallelic cMNR frameshift mutations within the TGFBR2 gene arise recurrently in most MSI colorectal tumors and are considered to drive MSI tumorigenesis." (PMID 28376875, 2017). "This protein subset is of particular clinical interest because it should reflect more accurately the situation existing in most primary MSI colorectal tumors with recurrent loss of TGFBR2 function." (PMID 28376875, 2017). "TGFBR2 exon 3 deletions are typically associated with colorectal tumors displaying microsatellite instability (MSI), a molecular marker for the loss of DNA mismatch repair (MMR)." (PMID 25315765, 2014). "It is important to note that results obtained from this TGFBR2-reconstituted system should reflect the inverse situation of the TGFBR2-deficient status in MSI primary colorectal tumors." (PMID 23468914, 2013). "Despite the majority of CRCs having deactivating TGF‐β pathway mutations (TGFBR1, TGFBR2, SMAD4, SMAD2, SMAD3), colorectal tumours produce significant amounts of TGF‐β, creating a TGF‐β rich environment, to which only the stromal compartment can respond." (PMID 35595718, 2022). "In general, this system inversely reflects the situation of primary MSI colorectal tumors that have lost TGFBR2 expression during tumor progression." (PMID 23468914, 2013). "Finally, SComatic also identified subclonal deleterious mutations in cancer driver genes frequently mutated in the cancer types analyzed, such as MLH1, TGFBR2 and KRAS in colorectal tumors, indicating that SComatic can discover subclonal driver mutations." (PMID 37414936, 2024). "TGFBR2 is one of the most interesting MSI target genes because it is part of a key signaling pathway in colon epithelial cells and found to be inactivated at high frequency by biallelic frameshift mutations in MSI colorectal tumors." (PMID 23468914, 2013).
esophageal cancer (6 papers, 2012 to 2024). A primary or metastatic malignant neoplasm involving the esophagus. "Current clinical trials, evaluate anti-MUC1 CAR T cells with PD-1 knockout in advanced esophageal cancer (NCT03706326) and anti-EGFR CAR T cells with TGFBR2 knockout in EGFR-positive solid tumors (NCT04976218)." (PMID 38962014, 2024). "For example, most of the genes on the trunk of sample ESCC12 (CCND1, EGFR, APC, TGFBR2, XPC, XPA, FLI1, and NUMA1) have been identified and initially reported on the esophageal cancer." (PMID 30540749, 2018). "On the contrary, the absence of TGF-β pathway activation also figures as a critical event in some situations, specifically when its signaling pathway disruption is mediated by the lack of Transforming Growth Factor Beta Receptor II (TGFBR2), as observed in colon and esophageal carcinomas." (PMID 26227631, 2015).
intestinal tumor (6 papers, 2015 to 2022). "TGFBR2 acts as a tumor suppressor, and the loss of TGFBR2 function may be an important determinant in the malignant transformation of intestinal neoplasms initiated by APC." (PMID 26061281, 2015). "In mouse models, Tgfbr2 inactivation in the intestinal epithelium accelerates the development of malignant intestinal tumors in combination with disruption of the Wnt-β-catenin pathway." (PMID 27835699, 2016). "Interestingly, only the combination of KRAS activation and TGFBR2 inactivation in mice have been found to induce formation of intestinal neoplasms." (PMID 28426742, 2017).
leukemia (6 papers, 2017 to 2026). A malignant (clonal) hematologic disorder, involving hematopoietic stem cells and characterized by the presence of primitive or atypical myeloid or lymphoid cells in the bone marrow and the blood. "Validated targets concentrated on key leukemia-related genes like PTEN, BCL2L11, CDKN1A, CCND1, RB1, E2F1, and TGFBR2." (PMID 42123456, 2026).
lymph node metastasis (6 papers, 2013 to 2019). "Loss of Tgfbr2 in a K‐ras‐induced LUAD mouse model has been found to induce a highly invasive phenotype associated with lymph node metastasis and reduced survival." (PMID 30761256, 2019).
Lynch syndrome (6 papers, 2008 to 2024). An autosomal dominant hereditary neoplastic syndrome characterized by the development of colorectal carcinoma and a high risk of developing endometrial carcinoma, gastric carcinoma, ovarian carcinoma, renal pelvis carcinoma, and small intestinal carcinoma. "Recent studies have shown that virtually all (99%) CRCs developing in Lynch syndrome patients display MSI-H; the most mutated genes exhibiting microsatellite repeats are ACVR2A, TGFBR2, EGFR, BPMR2, E2F4, MSH3, BAX and TCF7L2." (PMID 29652830, 2018). "Since it harbours coding microsatellites similar to TGFBR2, ACVR2A is one of the most frequently mutated genes in CRC in patients with Lynch syndrome and perturbation of TGFß signalling through truncating variants in ACVR2A is suggested to be an early event in CRC carcinogenesis." (PMID 34843512, 2021). "In the MSI pathway observed in Lynch syndrome, CRC formation is driven by the acquisition of mutations at the level of the coding sequences of genes, such as growth factor receptors (TGFBR2 and IGF2R), genes involved in apoptosis (BAX) and DNA repair (MSH3 and MSH6)." (PMID 29652830, 2018).
neuroblastoma (6 papers, 2013 to 2023). Neuroblastoma (NB) is the most common solid, extracranial childhood tumor. "The expression of MYCN, AURKA, TGFBR1, and TGFBR2 is directly inhibited by miR-186, which can inhibit the tumorigenetic potential of neuroblastoma." (PMID 37426487, 2023). "The role of RNF11 in the TGFβ pathway is of particular interest in neuroblastoma given our previous finding that the miR-17∼92 cluster components target TGFBR2 and SMAD2 as well as TGFβ downstream regulated genes CDKN1A, ITGA4, and SERPINE1." (PMID 23308108, 2013). "In neuroblastoma cells, the miR-17-92a cluster has been shown to impair TGF-β signaling pathway through miR-17 and −20a targeting of SMAD2, SMAD4 and transforming growth factor beta receptor 2 (TGFBR2)." (PMID 27650539, 2016). "Directly downregulates MYCN and AURKA in neuroblastoma cells, which can potentially have a negative impact on their survival; miR-186 upregulation in NK cells resulted in the downregulation of TGFBR1 and TGFBR2 and, thus, impaired the TGFβ1-dependent inhibition of NK cells’ cytotoxicity." (PMID 33530529, 2021).
osteosarcoma (6 papers, 2012 to 2024). A usually aggressive malignant bone-forming mesenchymal neoplasm, predominantly affecting adolescents and young adults. "The role of TGFBR2 in tumors varies across various cancer types; for example, the expression of TGFBR2 increases in lung metastasis of osteosarcoma." (PMID 39364312, 2024). "The most interesting inversely correlated miRNA/mRNA pairs in osteosarcoma cell lines included miR-9/TGFBR2 and miR-29/p85α regulatory subunit of PI3K." (PMID 23133552, 2012). "In osteosarcoma cell lines, miR-9 inversely correlated with the predicted target gene transforming growth factor, beta receptor II (TGFBR2)." (PMID 23133552, 2012). "An increase of miR-9 and reduced levels of TGFBR2 was confirmed in osteosarcoma clinical samples." (PMID 23133552, 2012). "For example, the SNHG1 lncRNA sequestered miR-302/372/373/520 and consequently activated TGFBR2 and RAB11A in invasive pituitary tumors, while DANCR acted as a decoy for miR-335-5p and miR-1972, thus promoting ROCK1-associated proliferation and metastasis in osteosarcomas." (PMID 30774556, 2019).
colitis (5 papers, 2012 to 2026). Inflammation of the colon. "We report a pediatric case of IBD with a TGFBR2 variant, presenting active colonic inflammation and pseudopolyposis, treated with adalimumab." (PMID 41426201, 2026). "After DSS administration, the body weight of colitis mice decreased, but this decline was reversed in Eocre-Tgfbr2 flox/flox mice, indicating a protective effect of TGF-β genetic knockout in preventing weight loss in colitis." (PMID 39214980, 2024). "Surprisingly, Tgfb1, Il17ra, Il23a, Il6ra, Ror1, Tnf, Tgfbr2, Ccr2, and Il17c were downregulated by cigarette smoke exposure in TNBS-induced colitis Gpr15−/− mice compared with similarly treated Gpr15+/+ mice." (PMID 40957881, 2025).